RNF2 (ring finger protein 2)
Diseases named in the same sentence as RNF2 in open-access papers (continued):
Sharing a sentence is not in itself a finding about the gene and the disease.
prostate carcinoma (9 papers, 2016 to 2024). A carcinoma that arises from epithelial cells of the prostate gland. "This provides a model for studying how PRC1/RNF2 alters prostate cancer cells to influence metastasis." (PMID 32929562, 2021). "Finally, FVB/NJ mice were inoculated with cells from their prostate cancer model (PtenPC−/−Smad4PC−/−) and treated with a small-molecule inhibitor of RNF2, identified in a screen of a compound library–inhibited metastasis." (PMID 32929562, 2021). "RNF2 has been proved to have oncogenic function in many kinds of cancers, but the function of RNF2 in prostate cancer (PCa) has not been evaluated." (PMID 28029659, 2017). "Several genes have been identified as epigenetic targets of RNF2; for example, cyclin-dependent kinase inhibitors 1A and 2A (CDKN1A and CDKN2A) were shown to be RNF2 targets in hepatic stem/progenitor cells, and thioredoxin interacting protein was reported to be an RNF2 target in prostate cancer." (PMID 33346749, 2020).
ovarian carcinoma (6 papers, 2017 to 2023). A malignant neoplasm originating from the surface ovarian epithelium. "Interestingly, higher expression of RNF2 induces cisplatin resistance in ovarian cancers, and its knockdown enhanced the radiosensitivity of lung cancer cell lines, suggesting its role in promoting tumorigenesis." (PMID 34224728, 2021).
bladder cancer (5 papers, 2017 to 2025). "RNF2 is frequently overexpressed in a broad spectrum of human cancers, including breast, prostate, and bladder carcinomas, where elevated expression is associated with poor prognosis and metastasis." (PMID 40831499, 2025). "RNF2 is upregulated in many human cancer types, and elevated RNF2 expression is an independent poor prognostic marker in pancreatic, breast, ovarian and bladder cancers." (PMID 33346749, 2020). "In addition, circ_100146 had been discovered to be upregulated in bladder cancer, which could facilitate cell proliferation and metastasis via the miR-149-5p/RNF2 axis." (PMID 34983607, 2022).
glioma (5 papers, 2021 to 2025). A benign or malignant brain and spinal cord tumor that arises from glial cells (astrocytes, oligodendrocytes, ependymal cells). "For example, circ-000834 can lead to the up-regulation of RNF2 by the sponge miR-433-3p, which in turn causes glioma cells to develop radioresistance." (PMID 36142355, 2022). "Hence, identifying RNF2-associated circRNAs is important for overcoming glioma radioresistance." (PMID 39877636, 2025). "Functionally, circ_0008344 performed as a miR-433-3p sponge to improve glioma radioresistance by augmenting the Ring finger protein 2 (RNF2) expression." (PMID 39877636, 2025). "As the role of KLF9 in oxidative stress has been widely reported, we therefore chose KLF9 as a downstream target for GPR17 and RNF2 to control ROS level in glioma cells." (PMID 34120140, 2021). "The Gliovis database showed that in tumor tissues, the expression of RNF2 was significantly higher than normal tissues, and RNF2 expression increased during glioma exacerbation, from Grade II to IV." (PMID 34120140, 2021). "The level of RNF2 was relatively higher in high-grade gliomas (WHO IV) than in normal brain tissues or LGGs (WHO II and III)." (PMID 34120140, 2021). "circ_0008344 downregulation impedes glioma growth and functions on the miR-433-3p/RNF2 axis to promote radiosensitivity in glioma." (PMID 35070998, 2021). "Accordingly, silencing RNF2 sensitizes glioma cells to radiation by enhancing apoptosis." (PMID 39877636, 2025). "A study indicated that the circ_0008344 expression was markedly higher in glioma with resistance to radiotherapy and subsequent experiment proved that the decrease of circ_0008344 inhibited glioma progression and enhanced the radiosensitivity in glioma by acting on miR-433–3p/RNF2 axis." (PMID 38075205, 2024). "KLF9 mediates the functions of GPR17 and RNF2 in glioma cells." (PMID 34120140, 2021). "RNF2 also promoted glioma cell proliferation and inhibited cell apoptosis." (PMID 34120140, 2021). "We also confirmed the protein levels of RNF2 in a cohort of glioma and normal brain tissue samples." (PMID 34120140, 2021). "Therefore, we hypothesized that KLF9 might mediate the regulatory effects of GPR17 and RNF2 on ROS levels and glioma tumorigenesis." (PMID 34120140, 2021). "On the other hand, both RNF2 and H2AK119ub recruitments were reduced upon GPR17 overexpression or activation by MDL29951 treatment in glioma cells." (PMID 34120140, 2021). "Taken together, our results indicated that GPR17 regulated RNF2 expression through a cAMP–PKA–p65 regulatory axis, and RNF2 mediated the functions of GPR17 in glioma cells." (PMID 34120140, 2021). "Besides, the protein levels of p-PKA and RNF2 were both significantly decreased in U87 xenografts after MDL29951 treatment, which further revealed the role of GPR17 activation in the control of PKA signaling activity and RNF2 expression in glioma." (PMID 34120140, 2021). "Knockdown of RNF2, but not RNF1, reduced the H2AK119ub level, indicating that RNF2 was the main factor for histone monoubiquitination in glioma cells." (PMID 34120140, 2021).
hepatocellular carcinoma (5 papers, 2018 to 2025). A malignant tumor that arises from hepatocytes. "Ring finger protein 2 (RNF2) is associated with the occurrence and development of hepatocellular carcinoma (HCC), but its function in ALD has not been explored." (PMID 40384855, 2025). "RNF2 is a RING domain-containing E3 ubiquitin ligase that mediate histone H2A mono-ubiquitination to repress gene transcription, but its expression patterns and molecular function in hepatocellular carcinoma (HCC) remain unclear." (PMID 37037816, 2023).
urothelial bladder carcinoma (4 papers, 2016 to 2023). "RNF2 (ring finger protein 2) is frequently overexpressed in several types of human cancer, but the status of RNF2 amplification and expression in urothelial carcinoma of the bladder (UCB) and its clinical/prognostic significance is unclear." (PMID 26869491, 2016).
breast tumors (3 papers, 2014 to 2023). "Using data from the TCGA database, we observed that RNF2 mRNA levels were increased in breast tumors compared with normal breast tissues." (PMID 36271315, 2023). "To analyze the clinical impact of RNF2 in human breast tumors, we further investigated data from a publicly available database." (PMID 36271315, 2023). "TCGA database analysis of 1080 breast tumors showed that RNF2 expression was positively correlated with estrogen signaling target genes expression (PDZK1, TFF1 and ESR1)." (PMID 36271315, 2023). "The subclass analysis showed that RNF2 mRNA levels were elevated only in ERα-positive breast tumors." (PMID 36271315, 2023).
cholangiocarcinoma (3 papers, 2021 to 2022). A carcinoma that arises from the intrahepatic biliary tree (intrahepatic cholangiocarcinoma) or from the junction, or adjacent to the junction, of the right and left hepatic ducts (hilar cholangiocarcinoma). "Other areas of investigation for targeted therapies in cholangiocarcinoma include human epidermal growth factor receptor 2 (HER2) and RNF2 mutations." (PMID 34439216, 2021). "MEG3 also can inhibit cholangiocarcinoma proliferation and invasion by inhibiting the major components of the PRC1 complex, B lymphoma Mo-MLV insertion region 1 (Bmi1), and RING finger protein 2 (RNF2)." (PMID 36551518, 2022).
esophageal squamous cell carcinoma (3 papers, 2022 to 2025). Esophageal squamous cell carcinoma (ESCC) is a type of esophageal carcinoma (EC) that can affect any part of the esophagus, but is usually located in the upper or middle third. "ETV4 transcription factor expression inhibits the expression of ubiquitin ligase RNF2, leading to increased expression of the key enzyme CPT1A involved in fatty acid oxidation, thereby playing a role in esophageal squamous cell carcinoma." (PMID 39944823, 2025).
liver fibrosis (3 papers, 2021 to 2025). "In a word, these data suggested that RNF2 regulates the development process of liver fibrosis via ERK/p38 signaling pathway." (PMID 33816485, 2021). "We chose LX-2 cells to research the effect of RNF2 in liver fibrosis, because the LX-2 cell line has main characteristics of HSCs, which are the central cells in the progress of liver fibrosis." (PMID 33816485, 2021). "In vitro, RNF2 activates the expression of Col1A1 and αSMA in LX-2 cells through the Erk/p38 pathway, which is considered to be a potential target for regulating liver fibrosis." (PMID 34853322, 2021). "Our experiment focused on the relationship between RNF2 and the process of liver fibrosis, especially in the regulation of HSCs." (PMID 33816485, 2021). "Therefore, understanding the roles of RNF2 in cell proliferation, inflammation, and further functions during liver fibrosis even other liver diseases is useful work, which brings a potentially therapeutic approach for the treatment of liver disease." (PMID 33816485, 2021). "Therefore, it is essential to clarify the effect of RNF2 in the process of liver fibrosis." (PMID 33816485, 2021). "However, the relationship between liver fibrosis and RNF2 remains to be further explored." (PMID 33816485, 2021). "RNF2 inhibition might be a promising therapeutic target for liver fibrosis." (PMID 33816485, 2021).
lung carcinoma (3 papers, 2014 to 2021). "Several clinical studies have shown that RNF2 is upregulated in several types of human cancer, including breast, nasopharyngeal, pancreatic, and lung carcinomas, which are associated with increased tumor growth and poor outcome." (PMID 27911266, 2017). "We describe the RRM1, RNF2, and Bmi1 interaction and co-localization, the mechanisms by which RNF2 and Bmi1 regulate RRM1 levels and cellular response to gemcitabine, and in situ protein levels in tumor specimens derived from patients with lung cancer." (PMID 24614341, 2014).
benign prostatic hyperplasia (2 papers, 2017 to 2022). A non-cancerous nodular enlargement of the prostate gland. "Here we show that PCa tissues showed higher RNF2 expression than the benign prostatic hyperplasia (BPH) tissues." (PMID 28029659, 2017). "In this paper, we showed that RNF2 is highly expressed in PCa tissues than the benign prostatic hyperplasia (BPH) tissues, and knockdown of RNF2 in PCa cells resulted in cell cycle arrest, increased apoptosis and inhibited cell proliferation." (PMID 28029659, 2017).
colorectal cancer (2 papers, 2020 to 2025). A primary or metastatic malignant neoplasm that affects the colon or rectum. "RNF2 expression was upregulated in colorectal cancer tissues and was associated with the tumor differentiation status, tumor stage and prognosis." (PMID 33346749, 2020). "To assess the function of RNF2 in colorectal cancer, we examined RNF2 protein levels in 313 paired colorectal cancer tissues and adjacent normal tissues." (PMID 33346749, 2020). "In colorectal cancer cell lines, downregulation of RNF2 inhibited cell proliferation and induced apoptosis." (PMID 33346749, 2020). "RNF2 is thus a potential prognostic marker and therapeutic target in colorectal cancer." (PMID 33346749, 2020).
esophageal carcinoma (2 papers, 2020 to 2026). A primary or metastatic malignant neoplasm involving the esophagus. "Consistently, previous publications have delineated the role of RNF2 in esophageal carcinoma growth." (PMID 32079144, 2020).
heart failure (2 papers, 2021 to 2022). Inability of the heart to pump blood at an adequate rate to meet tissue metabolic requirements. "The rnf2−/− larvae usually die within a week, most likely of severe heart failure." (PMID 34768802, 2021).
liver disease (2 papers, 2021 to 2025). "Based on the outstanding role of RNF2, finding new target drugs for liver disease may be subsequent in the future." (PMID 33816485, 2021).
Luo-Schoch-Yamamoto syndrome (2 papers, 2025). "Pathogenic RNF2 missense variants have recently emerged as causative alleles in individuals with neurodevelopmental disorders, including Luo-Schoch-Yamamoto syndrome (LUSYAM; OMIM: 619460)." (PMID 40831499, 2025). "De novo dominant missense variants in RNF2, the principal E3 ligase of PRC1, are the genetic basis of Luo-Schoch-Yamamoto syndrome." (PMID 40831499, 2025).
neuroblastoma (2 papers, 2016 to 2024). Neuroblastoma (NB) is the most common solid, extracranial childhood tumor. "The effects of RNF2 were studied in human postmortem IS brains, a rat model of IS, tunicamycin (TM)‐induced mouse neuroblastoma neuro2a (N2a) cells, and oxygen–glucose deprivation/reperfusion (OGD/R)‐induced SH‐SY5Y cells." (PMID 39614674, 2024).
Stroke (2 papers, 2024 to 2025). Sudden impairment of blood flow to a part of the brain due to occlusion or rupture of an artery to the brain. "Consistently, RNF2 levels in the nucleus were increased in the brain tissue from stroke patients and I/R rats and co‐existed with MANF under ischemic injury." (PMID 39614674, 2024). "Furthermore, our study identified several novel and common gene variants in stroke patients through WES, including COL4A2, PSEN2, NOTCH3, and RNF2." (PMID 41379817, 2025). "Given the functions of RNF2 in promoting the stabilization of MANF via monoubiquitination, we inferred that RNF2 might facilitate MANF nuclear translocation under stroke stress." (PMID 39614674, 2024). "In this study, we found that RNF2 was significantly upregulated in human postmortem brain tissue from patients with stroke and rat brain underwent middle cerebral artery occlusion (MCAO), which predominantly expressed in neurons and in the activated glial cells, such as microglia and astrocyte." (PMID 39614674, 2024).
triple-negative breast carcinoma (2 papers, 2018 to 2023). An invasive breast carcinoma which is negative for expression of estrogen receptor (ER), progesterone receptor (PR), and human epidermal growth factor receptor 2 (HER2). "In triple negative breast cancer, the deletion of RNF2 enhances the activation and infiltration of CD4 + -T and NK cells to promote anti-tumor immunity." (PMID 37037816, 2023).
cerebral infarction (1 paper, 2024). An ischemic condition of the brain, producing a persistent focal neurological deficit in the area of distribution of the cerebral arteries. "In this study, RNF2 overexpression by lateral ventricular injection of AAV‐RNF2 significantly reduced the volume of cerebral infarction and improved the neuron survival of cerebral ischemic rats." (PMID 39614674, 2024).
Cerebral ischemia (1 paper, 2024). Restriction of arterial blood supply to the brain associated with insufficient oxygenation to support the metabolic requirements of the tissue. "In contrast, RNF2 knockdown aggregated neuron apoptosis in either ER stress or OGD/R condition, suggesting that RNF2 confers protection against brain ischemia." (PMID 39614674, 2024). "Furthermore, MANF knockdown effectively abolished the protective effect of RNF2 overexpression after cerebral ischemia." (PMID 39614674, 2024). "Given that RNF2 overexpression obviously increased NeuN‐positive cells after I/R injury, we wondered whether RNF2 facilitates neuroprotection against cerebral ischemia via inhibiting neuronal apoptosis." (PMID 39614674, 2024). "However, severe cerebral ischemia could induce RNF2 expression in glial cells, including microglia and astrocytes, but the neurons are still a major source of RNF2, which is similar to the characteristic of MANF expression in the ischemic rat brain." (PMID 39614674, 2024). "Mechanistically, we found that RNF2 is an E3 ubiquitin ligase for the mesencephalic astrocyte‐derived neurotrophic factor (MANF), which confers protection against brain ischemia." (PMID 39614674, 2024). "Mechanistically, RNF2 interacts directly with MANF in nuclear and promotes its monoubiquitination, thereby maintaining the stability of MANF, which confers protection against brain ischemia." (PMID 39614674, 2024).
cervical cancer (1 paper, 2025). A primary or metastatic malignant neoplasm involving the cervix. "Among these, MMP1 and RNF2 are particularly noteworthy because of their close association with cervical cancer tumorigenesis, particularly in terms of invasiveness and metastasis." (PMID 40809844, 2025). "In-depth investigation into the mechanisms of RNF2 in cervical cancer will provide novel insights and approaches for its treatment." (PMID 40809844, 2025). "In this study, we identified five ubiquitination-related biomarkers (MMP1, RNF2, TFRC, SPP1, and CXCL8) that are significantly associated with cervical cancer." (PMID 40809844, 2025). "The five ubiquitination-related biomarkers (MMP1, RNF2, among others) identified herein have potential clinical applications in the diagnosis, prognosis, and therapeutic targeting of cervical cancer." (PMID 40809844, 2025). "In summary, RNF2 likely plays a significant role in the proliferation, resistance to radiotherapy and chemotherapy, and immune evasion of cervical cancer, positioning it as a potential therapeutic target." (PMID 40809844, 2025). "Intersection analysis revealed 18 genes that were significantly differentially expressed, including the five selected biomarkers (MMP1, RNF2, TFRC, SPP1, and CXCL8), which are significantly associated with cervical cancer progression." (PMID 40809844, 2025). "In cervical cancer, RNF2 may affect cell cycle progression and promote cancer cell proliferation by facilitating the ubiquitin-mediated degradation of key regulatory proteins involved in the cell cycle." (PMID 40809844, 2025). "Investigating RNF2 protein levels and activity in cervical cancer could yield valuable insights into its broad implications in the molecular landscape of the disease." (PMID 40809844, 2025). "On the other hand, RNF2 may promote the recruitment of immunosuppressive cells, such as MDSCs, and inhibit T cell activation, thereby regulating the immune escape capability of cervical cancer cells." (PMID 40809844, 2025). "Additionally, protein-level analyses, such as Western blot or immunohistochemistry (IHC), are recommended to confirm the expression levels of RNF2 and SPP1 in cervical cancer tissues." (PMID 40809844, 2025). "Notably, knocking down RNF2 enhances radiosensitivity and induces apoptosis in lung squamous cell carcinoma cells, suggesting that RNF2 may reduce the sensitivity of cervical cancer cells to radiotherapy and chemotherapy by participating in the DNA damage repair pathway." (PMID 40809844, 2025). "The lack of significant mRNA upregulation does not preclude the potential role of RNF2 in cervical cancer; it may be involved in mechanisms such as protein stability and subcellular localization." (PMID 40809844, 2025).
colon cancer (1 paper, 2023). "As a tumour suppressor, RNF2 E3 ligase promotes proliferation of colon cancer cells by increasing IRF4 degradation through K48‐linked ubiquitination." (PMID 37341064, 2023).
Fanconi anemia (1 paper, 2020). Fanconi anemia (FA) is a hereditary DNA repair disorder characterized by progressive pancytopenia with bone marrow failure, variable congenital malformations and predisposition to develop hematological or solid tumors. "Based on these data, we provide a model that BMI1 or RNF2 deficiency causes R-loop formation and TRCs at CFSs, which can be counteracted by the Fanconi Anemia proteins." (PMID 32142505, 2020). "Altogether, these results suggest that there is an increase in R-loop formation in RNF2 KO cells, and the Fanconi Anemia proteins FANCD2 and FANCI are necessary to prevent the R-loop-associated genomic instability in RNF2 KO cells." (PMID 32142505, 2020). "We further found that in the absence of RNF2, cells depend on the Fanconi Anemia fork-protective proteins for genome maintenance and survival." (PMID 32142505, 2020).